Y_RNA (Y RNA )
Gene: Miscellaneous RNA gene on chromosome 17 (50,386,145 to 50,386,246, reverse strand). Ensembl gene ENSG00000206824.
Homologues: Orthologues: chimpanzee Y_RNA (99% identical), macaque Y_RNA (95% identical). Paralogues in human: RNY3 (94% identical), Y_RNA (94% identical), Y_RNA (93% identical), Y_RNA (92% identical), RNY3P1 (91% identical), Y_RNA (91% identical), Y_RNA (90% identical), Y_RNA (89% identical), RNY3P14 (88% identical), RNY3P16 (88% identical), Y_RNA (88% identical), RNY3P11 (87% identical), and 99 more.